CTLA4 (cytotoxic T-lymphocyte associated protein 4)
Diseases named in the same sentence as CTLA4 in open-access papers (continued):
Sharing a sentence is not in itself a finding about the gene and the disease.
tumor (continued). "In addition, comparison of the mRNA expression levels of hub genes between tumors and normal tissues suggested that expression of CTLA4 in tumor tissues was significantly higher than the expression in normal tissues (P < 0.05)." (PMID 33014010, 2020). "Anti-CTLA-4 immunotherapy does not deplete Foxp3+ cells in human tumours, which suggests that their efficacy could be enhanced by modifying the Fc portions of the mAbs to enhance Fc-mediated depletion of intratumoral Tregs." (PMID 32680511, 2020). "However, treatment with even a very low dose of anti-CTLA-4 acts synergistically with low dose ACT to produce striking control of tumor growth, even where ACT alone was not effective." (PMID 31249570, 2019). "In patients with HCV and HCC treated with anti-CTLA-4, the majority had a decrease in viral load, including three patients with a transient complete viral response; however, anti-viral T cell responses did not correlate with tumor response." (PMID 31627733, 2019). "The rationale behind this combination is to exploit the different mechanisms of action: inhibiting CTLA-4 leads to differentiation of naïve T cells, which will later be able to infiltrate tumor tissues with no restraint on their anti-tumor activity mediated by PD-1/PD-L1 inhibition." (PMID 31383005, 2019). "Furthermore, while RT and combined therapies with IT-IC and/or anti-CTLA-4 had significant slowing of tumor growth compared to untreated tumors, none of the mice in any of the treatment groups achieved a complete response." (PMID 31810498, 2019). "Nevertheless, such MSI+ CYT-high tumor cells are not effectively eliminated by the immune system, due to the increased levels of several immune-inhibitory checkpoint molecules, such as PD-L1, PD-L2, CTLA-4, LAG3, TIGIT, IDO1 and VISTA." (PMID 31429779, 2019). "Both CTLA-4 and PD-1 blockade could potentiate in situ vaccination through intra-tumoral TLR9 activation with systemic administration, while local administration only effected sub-therapeutic improvements to the uninjected tumor." (PMID 31771649, 2019). "Furthermore, we found that the expression of PD-L2, CD80, CD86, and CTLA-4 are also elevated in cytomegalovirus and EBV-positive tumor patients, suggesting anti-PD-L2 and anti-CTLA4 immunotherapy may be effective in patients with these types of tumors." (PMID 30911684, 2019). "This may signify that a combination immunotherapy targeting these two molecules may encourage tumor-specific responses, avoiding non-specific or self-antigen specific immune responses, perhaps rendering such treatment less toxic than CTLA-4 blockade." (PMID 30941125, 2019). "Likewise, concomitant provision of CTLA-4 ICB and antagonists of either A2AR or A2BR leads to decreased tumor growth and metastasis formation, as well as to higher survival of tumor-bearing mice when compared to single treatments." (PMID 31244820, 2019). "Adding to this, when tumor-infiltrating CD8 T cells were isolated and cultured with tumor cells in vitro, they were able to kill the tumor cells, and CD8 T cells from anti-PD-1- and anti-CTLA-4-treated mice were able induce significantly more cancer cell death." (PMID 31804466, 2019). "Unlike microsatellite-stable (MSS) CRCs, MSI-H not only had a much more active immune microenvironment with greater tumor-infiltrating lymphocytes (TIL), but also showed cancer-specific upregulation of inhibitory checkpoints including programmed cell death protein 1 (PD-1) and CTLA4." (PMID 31639018, 2019). "The authors postulated that the combination of radiotherapy and CD40 agonism was able to disrupt and re-organise the links between the innate and adaptive immune systems in a non-redundant way, hence resulting in tumours that were re-sensitised to anti-PD-1 and anti-CTLA-4 therapy." (PMID 31091774, 2019).
tumor (continued). "Intriguingly, many studies are now analyzing tumor stem cells as a source of immune evasion, as they have been shown to selectively acquire expression of CD80, a surface ligand that dampens immune recognition by binding Cytotoxic T lymphocyte Antigen-4 (CTLA-4) present on activated T cells." (PMID 31167446, 2019). "Notably, the combination of local TLR9 and local CTLA-4 also significantly improved CD8 to Treg ratios in the untreated lesion reflecting improved mobilization of CD8s at the injected lesion, which then traffic to the left flank tumor." (PMID 31771649, 2019). "Therefore, ICB therapy to each receptor will modulate T cell responses in a non-redundant manner, with anti-CTLA-4 primarily affecting the priming of T cells and anti-PD-1 enhancing T cell activity in the periphery and tumor microenvironment." (PMID 30621125, 2019). "It was pointed out recently that 10 to 20% of patients who had received immunotherapy treated with anti-CTLA-4 antibody showed increases of their tumor sizes at 3 months after starting the administration but no more tumor progression occurred without any additional intervention." (PMID 31601857, 2019). "EMT that induces checkpoint-dependent resistance to anti-tumor immunity may render cancer cells nonresponsive to therapies targeting one or few checkpoints (e.g., anti-PD-L1 and anti-CTLA-4)." (PMID 31531020, 2019). "Furthermore, archaeosome vaccine formulations combined with anti-CTLA-4 and anti-PD-1 therapy, induced OVA-CD8+ T cells within the tumor and immunohistochemical analysis revealed the presence of CD8+ T cells associated with dying or dead tumor cells as well as within or around tumor blood vessels." (PMID 31771150, 2019). "In this study, tumours in antibiotic-treated or germ-free mice did not respond to CTLA-4 blockade; this defect was overcome by gavage with Bacteroides fragilis, by immunisation with B. fragilis polysaccharides, or by adoptive transfer of B. fragilis-specific T cells." (PMID 30413828, 2019). "Since all OS tumours had CD8+ T-cell infiltration (of varying degrees) inferred from CD8A gene expression, we wanted to investigate the expression level of several T-cell inhibitory receptors PD-1, Tim-3, LAG-3, and CTLA4 using the RNA-seq data to assess the functional state of these CD8 + TILs." (PMID 30674975, 2019). "This approach was employed during anti-CTLA-4 treatment in colon cancer xenograft models using a murine 89Zr-labelled anti-CD3 antibody ([89Zr]Zr-DFO-CD3) to quantify T-cell infiltration; interestingly high levels of infiltrations were found to precede tumour regression." (PMID 31656546, 2019). "We observed an expansion of PD-1+CTLA4+CD8 T cells after RT, consistent with recently published literature that this specific subset of cells may have an exhaustion phenotype and be responsible for anti-tumour immunity." (PMID 30318516, 2018). "Furthermore, anti-CTLA-4 antibodies effectively induce depletion of regulatory T (Treg) cells in tumor microenvironment but not in the peripheral lymphoid organs, which is strictly dependent on Fc receptor on host cells." (PMID 29713453, 2018). "Moreover, in the poorly immunogenic B16.F10 model, adding ADU-S100 to the ineffective combination therapy of anti-PD-1 and anti- CTLA-4 induced tumor-specific CD8+ T cell responses and tumor control, leading to multiple complete responses and durable immunity in surviving animals." (PMID 30400835, 2018). "This provides proof of concept that changes in gene expression in peripheral blood (as opposed to gene expression in tumor tissue or the organ involved directly by the toxicity) can predict for immune mediated toxicity following treatment with a CTLA-4 inhibitor." (PMID 30227886, 2018).
tumor (continued). "The authors concluded that both checkpoint blockade therapies targeted only specific tumor-infiltrating exhausted-like CD8 T cells and that the effect of these agents primarily differed in the expansion of inducible costimulator (ICOS) + Th1-like CD4 effector cells induced by the anti-CTLA-4 agent." (PMID 29520282, 2018). "When the host’s immune system is “primed” with CTLA-4 blockade to favor a balanced ratio of Teff cells >Tregs, a cytotoxic CD8+ T-cell response will predominate, resulting in conferred immunity to the cancer and regression of not only the primary tumor but of its metastatic deposits as well." (PMID 29644213, 2018). "Apart from the inhibitory surface receptors CTLA-4 and PD-1 several cytoplasmic proteins, such as ubiquitin ligases and kinases, downstream of the T cell receptor (TCR) act as negative regulators of T cell activation and may limit anti-tumor immune responses." (PMID 29794999, 2018). "The generation of an inflammatory milieu in the tumor microenvironment (TME) and infiltration of activated lymphocytes induce tumor escape mechanisms that exploit immune checkpoints to evade adaptive immune responses, including up-regulation of PD-L1 in TME and CTLA-4 in peripheral lymphoid tissues." (PMID 29970158, 2018). "Nowadays, immunotherapies, particularly immune checkpoint inhibition (ICI) of CTLA4 and PD1/PDL1, are increasingly used as a promising and effective systemic cancer treatment, boosting the immune response, and thus leading to successful immune recognition and tumor cell killing." (PMID 30577587, 2018). "Tellingly, neither PD-1 nor CTLA-4 blockade could significantly reduce tumor growth in the murine model, which was similar to findings from single-agent studies in patients with pancreatic cancer." (PMID 29482595, 2018). "The upregulation of alternative checkpoints as a compensatory mechanism might explain the lack of response or partial tumor regression observed in preclinical models and in cancer patients when treated with anti-CTLA-4 or anti-PD-1 monotherapy." (PMID 29520282, 2018). "However, the combination of vvDD-IL-2-RG and anti-PD-1/PD-L1 antibody, but not anti-CTLA-4 antibody, cured most of the advanced tumour-bearing mice." (PMID 30410056, 2018). "The interaction of CTLA-4 and its ligands generates an inhibitory signal and decreases or represses the viability of T cells.Blocking the interaction of CTLA-4 and ligandspromotes CD28 to bind the two ligands, activates T cells, improves the body’s immune response, and kills tumor cells." (PMID 30564277, 2018). "However, CD8+ TILs separated from human HCC tissues are functionally exhausted as determined by upregulated expression of PD-1, Tim-3, CTLA-4, and lymphocyte activation gene 3 (LAG-3) compared with those from human CHB tissues, tumor-free liver tissues, and peripheral blood." (PMID 30309387, 2018). "It is thought that the blockade of CTLA-4 most likely impacts the stage of T cell activation in the draining lymph nodes when CTLA-4 expressing Tregs remove CD80/CD86 from the surface of antigen-presenting cells, thereby reducing their ability to effectively stimulate tumor-specific T cells." (PMID 29644214, 2018). "Additionally, in the present study, we focused on the correlation between PD-L1 expression on tumor cells and TILs, but did not consider PD-1 or CTLA-4 expression on TILs." (PMID 29732001, 2018). "Thus, combination treatment with CTLA-4 and PD-1 pathway blockers should enable the creation of an immunogenic TME with subsequent clinical benefit for patients regardless of the quantity of TILs or expression PD-L1 in pretreatment tumor tissues." (PMID 29482595, 2018). "Although the mechanism by which CTLA-4 enhances the immunosuppressive function of Treg cells remains unknown, Treg cells-specific CTLA-4 knockout or blockade significantly inhibits their ability to regulate both auto-immunity and anti-tumor immunity." (PMID 29482595, 2018).
tumor (continued). "To test this hypothesis, in a comparison group we depleted CD8 T cells prior tumor implantation, rather than the standard approach of T cell depletion prior to RT, and treated with anti-CTLA4 and RT." (PMID 29725089, 2018). "Therefore, 9H10, the first and most extensively studied tumor immunotherapeutic anti-Ctla-4 mAb does not block the B7-Ctla-4 interactions." (PMID 29472691, 2018). "Interestingly, although tumor-infiltrating Foxp3− T cells expressed CTLA-4, albeit at lower levels, they were not depleted by anti-CTLA-4 mAbs." (PMID 29472691, 2018). "In contrast to CTLA-4, PD-1 acts via interactions with its ligands PD-L1 (also known as B7-H1 or CD274) and is involved mainly in T cell activity modulation in peripheral tissues as well as providing a major immune resistance mechanism within the tumor microenvironment." (PMID 28866656, 2018). "Despite the immunosuppressive role of CTLA-4, its association with disease prognosis is not clear; however, it should be noted that only a few studies have described the prognostic value of CTLA-4 levels in the tumor site." (PMID 29644214, 2018). "Blockage of CTLA-4 and PD-1 in murine solid tumor models has led to an increased expression of activation markers by T-cells, such as IFN-γ, IL-2, perforin, and granzyme; furthermore, these treatments have resulted in improved trafficking of activated T-cells to the tumor site." (PMID 30740109, 2018). "Since both mAbs showed comparable immunotherapeutic effect and comparable depletion of Treg cells in the tumor microenvironment, local depletion of Treg cells, rather than blockade of the mB7-CTLA-4 interaction, provides a unifying explanation for the therapeutic effect of anti-mouse CTLA-4 mAbs." (PMID 29472691, 2018). "Therefore, the combined mRNA expression of key signal transduction pathway components and regulators of the extracellular tumor microenvironment in combination with certain direct regulators of immune activity (ICOS, DPP4) appears to predict priming for responsiveness to CTLA-4 blockade." (PMID 28807052, 2017). "The authors also demonstrated that T cell receptor (TCR) clonality positively correlated with both treatment response and with pre-treatment immune scores (used to estimate immune activation, within the tumor microenvironment), with regards to PD-1, but not to CTLA-4, blockade." (PMID 29100459, 2017). "In addition to inhibiting the CTLA-4 inhibitory signal, recent work has suggested that selectively depleting regulatory T (Treg) cells at tumor sites, which happen to express the highest level of surface CTLA-4, is critical for CTLA-4 mAb-mediated antitumor effect." (PMID 29211042, 2017). "Moreover, we could demonstrate that expression of the immune checkpoint molecules CTLA-4, PD-1 and PD-L1 was increased on intratumoral and circulating T cells in HNSCC patients compared to healthy donors, reflecting an immunosuppressive tumor microenvironment." (PMID 28574843, 2017). "In conclusion, we hypothesize that CTLA-4 expression by tumor cells in locoregional LN+, but not PTs, may predict poor survival in NSCLC patients." (PMID 28707078, 2017). "Most recent are targeting two immuno-checkpoint receptors; CTLA4 (cytotoxic T-lymphocyte-antigen 4), PD-1 (programmed cell death 1) and its ligand PDL1, and show a remarkable efficacy against certain tumors, through re-activating cytotoxic T (Tc) cell mediated tumor killing." (PMID 28148223, 2017). "Hypothesizing that CTLA-4 is a candidate prognostic biomarker for inclusion in a NSCLC Immunoscore, we aimed to explore the prognostic impact of CTLA-4 in tumor epithelial and stromal cells of PTs from 536 resected stage I-IIIA NSCLC patients as well as in 142 matched lymph node metastases (LN+)." (PMID 28707078, 2017).
tumor (continued). "Regression of the irradiated and abscopal tumours was similar in mice bearing TSAshIfnar1 and control TSAshNS cells at the irradiated site, indicating that responsiveness of cancer cells to IFNβ was not required for 8GyX3+anti-CTLA4-induced tumour inhibition." (PMID 28598415, 2017). "Following intratumoral delivery in nude mice xenograft models, the armed replication-competent virus demonstrated an improved anti-tumor effect compared to the unarmed virus, despite the lack of immunological function the anti-human CTLA-4 mAb had in these mice." (PMID 28592330, 2017). "However, the molecular basis of ipilimumab-based anti-CTLA-4 blockade for tumor immunotherapy has not yet been fully revealed, which has restricted our understanding of this MAb." (PMID 28978021, 2017). "Likewise, we did not observe remarkable or statistically significant differences in the phenotypes of tetramer negative cells found within the tumours in response to anti-CTLA-4 treatment." (PMID 28916749, 2017). "Furthermore, sequencing of MEK inhibitors and anti-CTLA-4, with or without anti-PD-1/PD-L1, will be an important factor to consider in order to optimize their anti-tumor activity." (PMID 28807001, 2017). "This difference is likely due to the primary involvement of PD-1 in the regulation of peripheral effector responses within inflamed tissues and the tumor microenvironment, as opposed to CTLA-4, which primarily regulates the priming phase of the T cell response within the lymph nodes." (PMID 28233730, 2017). "However, immunization of TiRP mice before tumor induction with tamoxifen failed to prevent tumor onset, and this was not improved upon combination of vaccine with anti-CTLA4 and anti-PD1." (PMID 29123081, 2017). "We could not find any obvious tumor-derived factors upstream of the upregulation of Ctla4 and Lag3 in the MLL-LNs." (PMID 28472073, 2017). "However, we did not measure PD-L1 and CTLA-4 expression in the tumor microenvironment by this method, and this should be taken into consideration when assessing the potential clinical utility of immune checkpoint blockade agents." (PMID 29137242, 2017). "Combination of CTLA-4 and PD-1 blockade has only been found effective in a subset of syngeneic tumor models; non-responsive models may require additional therapies such as vaccines or radiation to elicit tumor-reactive T cells." (PMID 27610613, 2016). "This conclusion is consistent with recent studies reporting that interfering with regulatory T cell function by means of anti-CTLA-4 antibody therapy recruits new T cells into the anti-tumor response, rather than “releasing” already primed cells from Treg-dependent control." (PMID 27121060, 2016). "Since combination therapy significantly improved CD4+ non-Treg/Treg and CD8+/Treg ratios as compared to α-CTLA-4 or α-PD-1 monotherapy in tumours, we reasoned that combination therapy could more potently stimulate effector functions of TILs." (PMID 27498556, 2016). "Of note, the HER-2-specific cytotoxic CD8 response was three- to fourfold higher in the tumor/lungs than in the spleen, while the virus-targeted response (i.e., stimulated by MVA-specific E3L and F2L peptides) alone or in combination with anti-CTLA-4 was similar in both tissues." (PMID 26961085, 2016). "Thus, while the percentage of ICOS+ CD8+ T cells was significantly higher in the periphery with combination treatment, the responses observed in the tumor were similar in MVA-BN-HER-2-treated groups irrespective of anti-CTLA-4 treatment." (PMID 26961085, 2016). "In response to virus or HER2-p63 restimulation, a five- to tenfold increase in the magnitude of IFNγ+ T cells was found in mice treated with MVA-BN-HER2 compared to tumor-bearing mice that received no treatment (control) or CTLA-4 blockade alone, as shown by the relative size of the pie charts." (PMID 26961085, 2016).